TNF (tumor necrosis factor)
Diseases named in the same sentence as TNF in open-access papers (continued):
Sharing a sentence is not in itself a finding about the gene and the disease.
fibrosarcoma (continued). "Inhibitory activities of BTN-Kat and ITN-Kat toward recombinant human TNF were evaluated in TNF-dependent colorimetric MTT cytotoxicity assay with WEHI 164 murine fibrosarcoma cell line, which is sensitive to human TNF." (PMID 31544893, 2018). "In our study, we demonstrated that systemic pharmacologic TNF ablation leads to the delay in transplantable tumor growth of MCA 205 fibrosarcoma, accompanied by decreased accumulation of MDSCs." (PMID 27148266, 2016). "Macrophages infiltrate tumors and release cytolytic factors including tumor necrosis factor α (TNF-α) to destroy the tumor, and it was found that platelets reduced macrophage-mediated cytotoxicity in fibrosarcoma by inhibiting the effects of TNF-α." (PMID 28105409, 2016). "In the study, the antitumour effectiveness of TNF-α combined with electrochemotherapy with intravenous CDDP was evaluated in murine fibrosarcoma tumour model." (PMID 25810699, 2015). "Taken together, our results indicate indirect antitumour action of adjuvant TNF-α in SA-1 fibrosarcoma tumours treated with ECT with low CDDP doses." (PMID 25810699, 2015). "TNFα has been shown to inhibit OXPHOS in liver cells by subunit tyrosine phosphorylation of complex IV and to cause inhibition of complex I and II in fibrosarcoma cells." (PMID 24828117, 2014). "Mitochondrial STAT3 has been linked directly to increased ROS generation in at least two distinct signaling contexts: TNF-α-mediated necroptosis in L929 mouse fibrosarcoma cells and NGF-dependent neurite outgrowth in PC12 cells." (PMID 24671708, 2014). "Since uromodulin-bound TNF was still able to exert cytotoxic effects in L929 fibrosarcoma cells, it was proposed that the lectin-like domain of TNF has to be spatially distinct from its receptor binding sites." (PMID 23966993, 2013). "Most of the mutants considered were analysed in Jurkat cells, T-cells, or L929 murine fibrosarcoma cells, thus in very different cellular contexts (e.g. in response to TNF, Jurkat cells are resistant to cell death, whereas L929 cell lines undergo necrosis)." (PMID 20221256, 2010). "There are several previous reports that docosahexaenoic acid (DHA) the other primary ώ-3 PUFA found in fish oils, attenuates human monocyte apoptosis or murine fibrosarcoma necrosis induced by TNF-α." (PMID 18638380, 2008). "PEG-TNF-alpha s, in which 29% and 56% of lysine residues were coupled to PEG, had anti-tumour activity approximately 4 and 100 times greater than unmodified TNF-alpha in the murine Meth-A fibrosarcoma model." (PMID 7734321, 1995). "Treatment of tumour bearing mice (WEHI-164 and Meth A fibrosarcoma) with TNF alpha-MAb 32 complex resulted in a 5- to 10-fold enhancement in the potency of the cytokine in comparison to free TNF alpha." (PMID 1377483, 1992). "A high level of intratumoral TNF induction by BPV was also observed in mice bearing Meth A fibrosarcoma or Lewis lung carcinoma." (PMID 2206945, 1990). "The therapeutic effect against the Meth A fibrosarcoma was in parallel with the intratumoral TNF activity." (PMID 2206945, 1990). "Furthermore, DHA has been reported to antagonize TNF-α-induced necroptosis and autophagy in the L929 murine fibrosarcoma cell line." (PMID 35457223, 2022). "In vivo studies performed in a murine model of fibrosarcoma showed that low doses of bifunctional nanoparticles bearing isoDGR and TNF (corresponding to few nanoparticles per cell) delayed tumor growth and increased the efficacy of doxorubicin without worsening its toxicity." (PMID 33952242, 2021). "Tumor necrosis factor alpha (TNFα) signaling via TNFR1 and TNFR2 receptors was shown to be implicated in the regulation of SOD2 upregulation and resulting protection from chromosomal damage, constituting a radioadaptive response in mouse fibrosarcoma cells." (PMID 32932812, 2020).
fibrosarcoma (continued). "It is reported that the addition of exogenous ROS or agents that trigger an increase in endogenous ROS generation sensitize many types of cells (endothelial cells, hepatocytes, and fibrosarcoma cells) to TNF-induced apoptosis possibly through inhibition of NF-κB transcription of survival genes." (PMID 32089705, 2020). "Importantly, HS-1371 also prevented TNF plus zVAD-induced necroptosis in the mouse fibrosarcoma cell line, L929, suggesting that the inhibitor blocks activity of both mouse and human RIP3." (PMID 30237400, 2018). "In addition, Majumder and co-workers found evidence that IFN γ and TNF α act in synergy via p48 complexes with STAT-1α binding to this same ISRE site in the CXCL10 promoter of human fibrosarcoma lines." (PMID 25033426, 2014). "MMP-2 and-9 expression of chondrosarcoma and fibrosarcoma cells treated with TNF-α 10 ng/ml were downregulated by NM treatment in a dose-dependent manner with MMP-2 block at 1000 μg/ml NM and MMP-9 total block at 500 μg/ml NM in fibrosarcoma and 99% block at 1000 μg/ml in chondrosarcoma." (PMID 24085323, 2013). "Determination of TNF-α was performed by a bioassay based on the cytotoxic effect of TNF-α on the mouse fibrosarcoma cell line WEHI 164 subclone 13 and a murine TNF-α standard (code 88/532; National Institute for Biological Standards and Control, South Mimms, UK)." (PMID 23388469, 2013). "Irradiated SHE cells treated continuously with TNF-alpha could be subcultured over 40 passages and produced fibrosarcomas upon inoculation into nude mice." (PMID 9579824, 1998). "Among inflammatory cytokines, tumor necrosis factor (TNF)-α stimulates MMP-9 biosynthesis in human fibroblasts, fibrosarcoma, and smooth muscle cells." (PMID 40565017, 2025). "This view is supported by the results of in vivo studies showing that G4 fused to TNF, an antitumor cytokine, can enhance the therapeutic effects of this cytokine in the WEHI-fibrosarcoma murine model." (PMID 38289472, 2024). "TNFα has been shown to promote HSPC activation and myelopoiesis in mice bearing subcutaneous MC57 fibrosarcoma tumors." (PMID 36561751, 2022). "Upon concomitant inhibition of IAPs with SM‐164, TNF potently triggered formation of complex‐II, caspase activation (Fig EV2B) and cell death in the human fibrosarcoma cell line HT1080." (PMID 32419365, 2020). "Studies have shown that TNF-alpha can inhibit the production and accumulation of MPE and prolong the survival of fibrosarcoma-bearing mice." (PMID 32552897, 2020). "Using pharmacological inhibition of human TNF in humanized mice (hTNF KI) with either etanercept or infliximab, we demonstrated that in mice transplanted with MCA 205 fibrosarcoma, MDSC accumulation and tumor growth were significantly diminished." (PMID 27148266, 2016). "Intratumoral administration of pardaxin inhibited tumor growth, possibly by downregulating Th1-type cytokine production (TNF-α and IFN-γ) and inducing apoptosis of fibrosarcomas by decreasing the Bax/Bcl-2 ratio and activating caspase-3." (PMID 23015777, 2012). "In fibrosarcoma cells for example, BCL2A1 was rapidly induced after TNF-α stimulation." (PMID 35260587, 2022). "Previous studies have demonstrated that the pan-caspase inhibitor zVAD-fmk induces necroptosis in different cellular models, including in the L929 fibrosarcoma and in the BV2 murine microglial cell lines, by a mechanism that most likely depends on TNF autocrine secretion." (PMID 34069782, 2021). "Here we report that A179L enhanced TNF-α or TSZ (TNF-α, Smac, and Z-Vad)-induced receptor-interacting protein kinase (RIPK1), RIPK3, and mixed lineage kinase domain like peudokinase (MLKL) phosphorylation in L929 cells, a murine fibrosarcoma cell line." (PMID 34960759, 2021). "Finally, we analyzed the anti-tumor activity and toxicity of 1-Au/TNF and 2-Au/TNF using nanodrug doses equivalent to 3 μg of bioactive TNF, administered intravenously to immunocompetent mice bearing subcutaneous WEHI-164 fibrosarcomas." (PMID 34124009, 2021).
fibrosarcoma (continued). "Nanoparticles functionalized with both iso1 and TNF induced tumor eradication in WEHI-164 fibrosarcoma-bearing mice more efficiently than nanoparticles lacking the iso1 targeting moiety." (PMID 34124009, 2021). "Treatment with TNF resulted in the formation of the TNF receptor signalling complex‐I (TNFR‐SC, also referred to as complex‐I) in the human fibrosarcoma cell line HT1080, as evidenced by the recruitment of bona fide TNFR‐SC components such as RIPK1, SHARPIN and TRADD (Fig EV2A)." (PMID 32419365, 2020). "ZFSC reduced IFN-γ and TNF-α content in the serum of HT-1080 tumor-bearing mice and inhibit PD1 and PDL1 and suggested that the antitumor mechanism of ZFSC on human fibrosarcoma could be attributed to inhibition of the PDL1/PD1 pathway." (PMID 27493673, 2016). "It has been shown that necroptosis—caspase-independent programmed necrotic cell death—can be induced by treatment with tumor necrosis factor (TNF) in the L929 murine fibrosarcoma cell line, even in the absence of a caspase inhibitor." (PMID 27739412, 2016). "This view is supported by the results showing that 5a-HSA could enhance, in the WEHI-164 fibrosarcoma model, the anti-tumor activity of S-NGR-TNF, a targeted inflammatory cytokine consisting of tumor necrosis factor-alpha (TNF) fused to a tumor vasculature-homing peptide containing the NGR sequence." (PMID 40055773, 2025). "To identify novel necroptosis inhibitors for potential clinical application, we screened the FDA-approved drug library using a well-established necroptosis model in mouse fibrosarcoma L929 cells, which are sensitive to TNFα-induced necroptosis even in the absence of caspase inhibitors." (PMID 37620300, 2023). "TNFα is also essential for the accumulation of immunosuppressive myeloid cells (CD11b+GR1+) and for tumor growth in mice inoculated subcutaneously with FB61 fibrosarcoma or J558L plasmacytoma cells, and for disease progression in chemically-induced skin cancer models." (PMID 36561751, 2022). "In addition, it has been demonstrated that L929 cells, a mouse fibrosarcoma cell line, subjected to TNF-induced necroptosis failed to induce pro-inflammatory cytokine production in macrophages." (PMID 27250033, 2016). "Whereas necroptosis has been induced in the presence of caspase inhibitors in many types of cells, it has been reported that necroptosis can be induced by the treatment with tumor necrosis factor (TNF) in the L929 murine fibrosarcoma cell line, even in the absence of caspase inhibitors." (PMID 27739412, 2016). "Taurolidine has previously been shown to enhance Fas-Ligand mediated cell death and a xenograft study using recombinant TNF in the treatment of mouse fibrosarcoma revealed that Taurolidine reduced the toxicity of TNF without decreasing the anti-tumor efficacy of TNF." (PMID 19077262, 2008). "In an experimental fibrosarcoma metastasis model, a single injection of low-dose recombinant human or mouse TNF prior to, but not after, fibrosarcoma inoculation increased the amount of lung metastasis, suggesting that TNF may enhance the vascular adhesion of tumor cells." (PMID 33917839, 2021). "Iso1Au/TNF and iso1Au/TNF + IL12 showed similar anti-tumor effects in the murine fibrosarcoma model, when used alone or in combination with chemotherapy, suggesting that the addition of IL12 does not increase the anti-tumor effects of iso1Au/TNF in this model." (PMID 33952242, 2021). "Unlike the results reported for the fibrosarcoma cells, CHOP mRNA was not increased in the presence of TNFα." (PMID 22417670, 2012). "According to this view, we found that extremely low, nontoxic doses of iso1Au/TNF or iso1Au/TNF + IL12, corresponding to 3–6 × 107 nanoparticles (equivalent to 5–10 pg of TNF), were sufficient to exert synergistic effects with doxorubicin in the WEHI-164 fibrosarcoma model." (PMID 33952242, 2021).
gestational diabetes (76 papers, 2006 to 2025). Carbohydrate intolerance first diagnosed during pregnancy. "Elevated TNF-α levels can worsen insulin resistance, which is associated with the development of gestational diabetes mellitus (GDM)." (PMID 40431246, 2025). "An increase in the TNF-α/IL-10 ratio potentially causes early and late pregnancy complications, mostly implantation failure, fetal loss, hypertensive syndromes, and gestational diabetes." (PMID 37887854, 2023). "In women with gestational diabetes, levels of the anti-inflammatory cytokine, adiponectin, are negatively associated with gestational diabetes while TNF-alpha and its soluble receptors sTNFR-1 and sTNFR-2 are positively associated." (PMID 22479352, 2012). "Taken together, there is biological plausibility behind our observed association, but future, better powered studies are needed to confirm whether TNF is implicated in the pathology of gestational diabetes." (PMID 40937292, 2025). "The loss of the control of the production of these cytokines, with increase of TNF-α, is related to the risk for developing obstetric complications, particularly recurrent fetal loss, gestational diabetes mellitus, hypertensive syndromes, and fetal growth restriction." (PMID 22462002, 2012). "Increased levels of TNF-α and IL-6 may contribute to placental dysfunction, impaired nutrient transport, and inflammatory disruption of the utero-fetal interface, factors that have been implicated in the pathogenesis of gestational diabetes mellitus." (PMID 40722699, 2025). "High levels of IL-6 and TNF-α have been positively associated with gestational diabetes mellitus (GDM)." (PMID 33806342, 2021). "However, rs9939609 was associated with increased TNFα in Mexican women with gestational diabetes." (PMID 32076432, 2019). "The results of the study suggested that regulation of TNF-α may provide an important target for physiological and pharmacological interventions designed to reduce the risk of adverse pregnancy outcomes related to gestational diabetes." (PMID 31448006, 2018). "Placentas from women with gestational diabetes release greater amounts of TNF in response to a glucose stimulus than those from women without." (PMID 40937292, 2025). "A further study has reported that in vitro treatment using AR-42 enhances the secretion of IL-1β, TNFα and IL-6 in monocytes obtained from patients with gestational diabetes mellitus." (PMID 37728477, 2023). "Expression levels of chemerin, IL-6, and TNF-α are increased in the peripheral blood of patients with gestational diabetes." (PMID 37964253, 2023). "The expression of chemerin, fatty acid binding protein 4 (FABP4), and the inflammatory factors IL-6 and TNF-α are increased in the peripheral blood of gestational diabetes patients." (PMID 37964253, 2023). "TNF-α has also been found to correlate inversely with insulin sensitivity in pregnant women with normal glucose tolerance and in women with gestational diabetes." (PMID 31828161, 2019). "Multiple binary logistic regression analysis of the effects of AIP and Log (adiponectin /TNF-α) on gestational diabetes mellitus." (PMID 29387323, 2018). "Women with gestational diabetes have higher concentration of inflammatory cytokines including IL-6, IL-10, and TNF-α compared with healthy pregnant women." (PMID 29385062, 2018). "Serum level of TNF-α was significantly higher among the pregnant women with gestational diabetes mellitus compared to the controls (2.50 ± 0.30 vs. 2.10 ± 0.30 pg/ml, p < 0.05)." (PMID 31448006, 2018). "This study has shown that the pregnant women with gestational diabetes mellitus have higher serum TNF-α levels than the pregnant women with normal gestation." (PMID 31448006, 2018). "We recommend larger prospective studies within the population that would examine the mechanism of alteration of the maternal circulating TNF-α level and its pattern from first through third trimester in pregnant women with gestational diabetes mellitus." (PMID 31448006, 2018).
gestational diabetes (continued). "Furthermore, elevated levels of certain inflammatory markers, such as tumor necrosis factor-alpha (TNF-α), have been implicated in the pathophysiology of gestational diabetes and associated fetal growth abnormalities." (PMID 37374343, 2023). "Thus, gestational diabetes is accompanied by increased expression of TNF-α and IL-6, with the exacerbation of an inflammatory state in the placenta." (PMID 37964253, 2023). "Hence, puerarin can reduce the expression of TNF-α and improve insulin resistance in gestational diabetes rats, suggesting the promising potency of puerarin in the remedy of gestational diabetes." (PMID 36358493, 2022). "DHA supplementation has also been found to decrease gene expression of inflammatory cytokines interleukin-1 (IL-1) and tumor necrosis factor α (TNFα) and increase gene expression of peroxisomal proliferator-activated receptor γ (PPARγ) in women with gestational diabetes." (PMID 36615797, 2022). "Mothers with gestational diabetes have higher levels of TNF-alpha, leptin and visfatin and lower levels of adiponectin that, in turn, might have a significant impact on the development of the immune response in infancy." (PMID 34682108, 2021). "This study suggests that IL-6 and TNF-α are correlated with gestational diabetes mellitus." (PMID 32280713, 2020). "The up-regulation of miR-452 in HUVEC from infants of mothers with gestational diabetes might be a defense mechanism to down-regulate TNFα, CCL2, and RETN in HUVEC." (PMID 31013606, 2019). "While ethnicity is one of the factors that influence production of cytokines during pregnancy, studies on the association between alterations in the maternal circulating level of TNF-α and development of gestational diabetes mellitus among black African women are limited." (PMID 31448006, 2018). "In vivo studies further support these findings: in gestational diabetes mellitus (GDM) rat models, berberine suppresses IKKβ phosphorylation and nuclear translocation of NF-κB p65 in liver tissue, thereby reducing TNF-α levels in both serum and liver." (PMID 41471379, 2025). "This study elucidates a novel correlative association between gestational diabetes mellitus (GDM) and maternal behavioral deficits, accompanied by altered FBN1 gene expression, elevated TNF-α, and disrupted serotonin signaling in the prefrontal cortex (PFC)." (PMID 41399726, 2025). "Recent studies indicate that OSA events positively correlate with systemic inflammation in both normal pregnancies and those with gestational diabetes mellitus (GDM), as indicated by higher circulating levels of TNF-α, IL-1β, IL-8, and IL-10." (PMID 38339130, 2024). "One study suggested a direct association between serum concentrations of 25(OH)D and Interleukin-8 (IL-8), macrophage inflammatory protein (MIP), and TNF-α levels in mothers with gestational diabetes mellitus (GDM)." (PMID 37891486, 2023). "Furthermore, the current study suggests that IL-6 and TNF-α are correlated with gestational diabetes mellitus, but further study is necessary to explain whether they have causal relationship." (PMID 32280713, 2020). "Given the compelling evidence that inflammatory markers play a role in pre-term births, including IL-6 and TNF-alpha, this work adds to the literature by suggesting that these markers may operate through onset of medical conditions in pregnancy, such as gestational diabetes." (PMID 31568495, 2019). "An analysis of the blood of patients with gestational diabetes mellitus (GDM) has demonstrated reduced CD4+CD25+ Treg cell numbers and increased pro-inflammatory cytokines IL-6 and TNF-a." (PMID 38732104, 2024). "Reduced levels of TNF-α, IL-1β, and IL-6 during KLF9 silencing suggest suppressed inflammation in gestational diabetes mellitus." (PMID 37940560, 2023).